C18orf15 (chromosome 18 putative open reading frame 15)
Synonyms: FLJ31338; HsT3231
Gene: Gene on chromosome 18 (13,239,543 to 13,242,076, forward strand). Ensembl gene ENSG00000279020.
Subcellular location: Membrane
Diseases named in the same sentence as C18orf15 in open-access papers:
C18orf15 is named in the same sentence as 1 disease in open-access papers, as found by Europe PMC text mining. Sharing a sentence is not in itself a finding about the gene and the disease. The quoted sentences say what the papers report.
viral meningitis (1 paper, 2024). Inflammation of the membranes surrounding the brain and spinal cord due to a viral infection. "In viral meningitis specific co-expression networks, a total of 9 significantly upregulated lncRNAs (AC243830.1, AC092111.1, CEROX1, AC246817.2, FAM66C, LINC01535, LINC02848, CHKB-DT, and C18orf15) were identified." (PMID 38347610, 2024).